CAPN2 (calpain 2)
Diseases named in the same sentence as CAPN2 in open-access papers (continued):
Sharing a sentence is not in itself a finding about the gene and the disease.
prostate carcinoma (continued). "In conclusion, our present findings show that DMDP-1 induces autophagy and activates calpain-2, while DMDP-2 inhibits autophagy, activates cathepsin B and calpain-2, both leading to caspase-independent cell death in human prostate cancer cells." (PMID 26974436, 2016). "Therefore, we showed the important roles of CAPN2 in the development and progression in CRPC cells, suggesting a new therapeutic intervention for treating castration-resistant prostate cancer patients." (PMID 28280729, 2017). "Following our previous research studies, our present data further define the key role of calpain 2 and not calpain 1 in prostate cancer progression, especially in cancer invasion and metastasis with its overexpression and enhanced activity in AR-negative prostate cancer cells." (PMID 24297527, 2014). "Furthermore, calpain 2 can also cleave AR to generate a truncated, functional AR without ligand-binding domain in androgen-sensitive prostate cancer cells, which enables cancer cell adaptation to androgen-independent growth and proliferation during androgen-deprivation treatment." (PMID 24297527, 2014).
colorectal cancer (9 papers, 2017 to 2024). A primary or metastatic malignant neoplasm that affects the colon or rectum. "The authors of this study suggested that calpain 2‐dependent IκB degradation mediates CPT‐11 secondary resistance in colorectal cancer xenografts." (PMID 29210197, 2018). "Recent studies have identified calpain 2 as an actor of the resistance of colorectal cancer cells to irinotecan, we have thus studied the potential implication of ubiquitous calpains in the resistance to oxaliplatin." (PMID 29262595, 2017). "In colorectal cancer, a recent study has shown that calpain 2 is involved in the resistance of cancer cells to irinotecan." (PMID 29262595, 2017). "The reduction in calpain-2 expression in xenograft tumours may serve as a novel outcome to complement existing anti-VEGF therapies for colorectal cancer such as Bevacizumab." (PMID 31217905, 2019). "1,4-dihydroxy quininib reduced calpain-2 expression in HMEC-1 cells and in an in vivo xenograft model of colorectal cancer." (PMID 36698840, 2022).
glioblastoma (8 papers, 2012 to 2025). The most malignant astrocytic tumor (WHO grade IV). "Their findings back the idea that calpain 2 expression is essential for glioblastoma cell invasion within the brain’s microenvironment." (PMID 40940872, 2025). "Calcium-dependent calpain proteases, in particular calpain-2, are more abundant in glioblastoma compared to normal brain and increased in patient-matched initial and recurrent glioblastomas." (PMID 36932402, 2023). "Moreover, the knockdown of calpain 2 hindered the glioblastoma cell invasion within the zebrafish brain and organotypic mouse brain slices." (PMID 40940872, 2025). "We observed a strong overexpression of calpain-2 in glioblastoma on both, protein and mRNA levels." (PMID 36932402, 2023). "Calpain 2 is a key downstream effector of calcium ions, facilitating glioblastoma cell invasion." (PMID 31601895, 2019). "Calpain-2 can also increase MMP2 activity to promote glioblastoma cell invasion." (PMID 27453531, 2016). "Another study suggested that calpain 2 could affect glioblastoma cell invasion by regulating MMP-2 activity." (PMID 23855590, 2013). "In the present study, we used patient samples of initial and recurrent glioblastoma as well as of non-malignant brain tissue to study the expression profiles of calpain-1 and calpain-2." (PMID 36932402, 2023). "Furthermore, calpain-2 has been reported to increase MMP2 activity, resulting in enhanced glioblastoma cell invasion." (PMID 27453531, 2016).
lung cancer (6 papers, 2009 to 2025). A malignant neoplasm involving the lung. "Indeed, treatment of A549 lung cancer cells with PD98059 caused a decrease in the expression of calpain-2." (PMID 19568240, 2009). "Immunohistochemical analysis revealed that the lung tissues of patients with ILD expressed higher levels of KL-6/CAPN2/SP-B than those of healthy donors and the paracancerous tissues of patients with lung cancer." (PMID 40750896, 2025). "From these results, we confirmed that hnRNPK/LINC00263/miR-147a/CAPN2 regulatory axis is very closely related to the malignant phenotype of lung cancer cells." (PMID 33731671, 2021). "All the cells tested showed suppression of CAPN2 expression as observed in HeLa and lung cancer cells." (PMID 33731671, 2021). "Taken together, our findings support the view that fibronectin induces the activation of FAK which then activates both the ERK1/2/MMP9 and ERK1/2/calpain-2 pathways to promote lung cancer cell invasion and migration, respectively." (PMID 19568240, 2009). "In this study, we examined the FAK signalling pathways in relation to calpain-2 and RhoA in fibronectin-mediated lung cancer cell migration and invasion." (PMID 19568240, 2009). "In this study, we propose that fibronectin-induced stimulation of FAK that causes lung cancer cell migration and invasion occurs by the activation of MMP9/calpain-2 and MMP9/RhoA through the ERK and PI3K/Akt signalling pathways, respectively." (PMID 19568240, 2009). "It has been reported that CAPN2 might promote lung cancer progression by activating EGFR/pAKT signaling pathway, and also contribute to the resistance to paclitaxel or EGFR-TKI21,22." (PMID 34728688, 2021). "Our data suggest that fibronectin-mediated activation of FAK that leads to lung cancer metastasis could occur through ERK or PI3K/Akt regulation of MMP9/calpain-2 or MMP9/RhoA activity, respectively." (PMID 19568240, 2009). "Fibronectin is known to induce activation of FAK via extracellular signal-regulated kinase (ERK) or PI3K/Akt to increase matrix metalloproteinase (MMP)-9/calpain-2 or MMP-9/RhoA activity, respectively, and lead to lung cancer metastasis." (PMID 26517522, 2016). "Using western blotting, we found that A549 cells treated with PD98059 showed decreased expression of both MMP9 and calpain-2, suggesting that ERK1/2 regulates the expression of these proteins in A549 lung cancer cells." (PMID 19568240, 2009). "Although there are numerous suggestions that the ECM promotes cancer cell migration and invasion through FAK signalling, the mechanism by which ECM fibronectin regulates FAK activity in lung cancer cells, particularly in relation to calpain-2 and RhoA, has not yet been explored in detail." (PMID 19568240, 2009).
ovarian carcinoma (6 papers, 2017 to 2021). A malignant neoplasm originating from the surface ovarian epithelium. "have reported that high expression of CAPN2 protein was significantly associated with resistance to platinum-based adjuvant chemotherapy in ovarian cancer." (PMID 32382656, 2020). "Results from previous ovarian cancer studies confirm that the calpain system is associated with patient overall survival, particularly calpain-2 expression." (PMID 30737623, 2019). "Abnormal expression of CAPN2 is closely associated with poor prognosis of ovarian cancer patients." (PMID 33731671, 2021). "In addition, higher expression of CAPN2 is associated with pancreatic cancer and the resistance to platinum-based adjuvant chemotherapy in ovarian cancer." (PMID 31884422, 2019). "In conclusion, both the previous and the current ovarian cancer patient-based studies indicate that calpain-2 expression is adversely associated with overall survival, with calpain-4 and calpastatin expression also negatively associated with overall survival in the current study." (PMID 30448882, 2019). "Calpain-1, calpain-2, calpain-4 and calpastatin expression were evaluated in primary ovarian carcinomas (n = 575) by immunohistochemistry." (PMID 30448882, 2019). "We have previously reported on the prognostic importance of the calpain family of proteins in ovarian cancer, especially calpain-2." (PMID 30737623, 2019). "Results from previous ovarian cancer studies confirm that calpain-2 is an important factor in cancer survival." (PMID 30737623, 2019). "In addition, abnormal CAPN2 expression was associated with patients progression-free survival (PFS) and overall survival (OS) in ovarian cancer, and served as a specific prognostic indicator." (PMID 29228653, 2017).
Alzheimer disease (5 papers, 2016 to 2022). A progressive, neurodegenerative disease characterized by loss of function and death of nerve cells in several areas of the brain leading to loss of cognitive function such as memory and language. "Calpain-2 hyperactivity was detected in synaptosomes of Alzheimer disease (AD) patients during pre-symptomatic phases." (PMID 36430329, 2022). "Given that tau hyperphosphorylation is a hallmark of several neurological disorders, including Alzheimer’s disease (AD) and traumatic brain injury (TBI), the authors tested whether they could link TBI-induced calpain-2 activation, via PTPN13 cleavage, to tau hyperphosphorylation." (PMID 36755664, 2022).
breast tumor (5 papers, 2018 to 2023). "Calpain-2 expression was increased in breast tumors in accordance with the increase in FN expression." (PMID 31000696, 2019). "We determined if the effects of baicalein on the expression of FN, calpain-2, E-cadherin, and vimentin in breast tumor tissue reflected the in vitro results." (PMID 31000696, 2019). "A knockdown study of CAPN2 in breast tumour cells resulted in reduced cell migration, proliferation, as well as reduced Akt activation, increased FoxO nuclear localization and p27 expression." (PMID 29545918, 2018). "In fact, high expression of calpain 2 in breast tumor patients is associated with negative outcome of survival." (PMID 34589605, 2021). "Furthermore, baicalein also decreased the expression of calpain-2 in breast tumors in MMTV-PyMT mice." (PMID 31000696, 2019). "Likewise, calpain-1 and calpain-2 could be considered the proteases of two faces controlling physiological mammary gland homeostasis, but also promoting breast tumor progression." (PMID 37795261, 2023).
pancreatic cancer (5 papers, 2019 to 2024). "CAPN2, a calcium-dependent cysteine protease, has been implicated in cancer progression, including pancreatic cancer." (PMID 39434688, 2024). "However, the role and underlying regulatory mechanisms of CAPN2 in pancreatic cancer (PC) are still unknown." (PMID 35707527, 2022). "This demonstrates that CAPN2 plays a significant role in promoting the proliferation of pancreatic cancer organoids." (PMID 39434688, 2024). "Elevated CAPN2 levels are linked to advanced tumor stages and poor prognosis, making the METTL16–MROH8–TBP–CAPN2 axis a potential therapeutic target for pancreatic cancer." (PMID 39434688, 2024). "This study reveals a novel regulatory axis involving METTL16, MROH8, and TBP that modulates CAPN2 expression, contributing to the suppression of pancreatic cancer progression." (PMID 39434688, 2024). "This study thus proposes a novel regulatory axis involving METTL16, MROH8, and CAPN2, expanding our understanding of how m6A modifications influence pancreatic cancer progression and offering potential new therapeutic targets." (PMID 39434688, 2024). "Analyzing mRNA profiles of different pancreatic cancer cell lines and normal pancreatic cell lines, we found that CAPN2 was upregulated in tumor cell lines compared to normal pancreatic cell lines." (PMID 39434688, 2024). "Our study found that METTL16 suppresses pancreatic cancer progression by downregulating CAPN2 via m6A-mediated regulation." (PMID 39434688, 2024). "In this study, we investigated the prognostic significance of CAPN2 expression in pancreatic cancer tissues." (PMID 35707527, 2022). "In pancreatic cancer, it has been reported that CAPN2 can induce apoptosis of pancreatic cancer cells and is related to poor prognosis." (PMID 35783277, 2022). "The protein and mRNA levels of CAPN2 were evaluated in three pancreatic cancer cell lines, Sw1990, Capan-2, and Panc-1, and a normal human pancreatic duct cell line by Western blotting and RT–qPCR." (PMID 35707527, 2022). "Correlation between CAPN2 expression and clinicopathologic features of 64 patients with pancreatic carcinoma." (PMID 35707527, 2022). "Furthermore, the relationship of CAPN2 messenger RNA (mRNA) and protein in pancreatic cancer cells and pancreatic HTERT-HPNE cells was studied." (PMID 35707527, 2022). "Finally, CAPN2 significantly promotes the proliferation and metastasis of pancreatic cancer cells." (PMID 39434688, 2024). "Subsequent experiments confirmed this hypothesis; we found that METTL16 inhibits CAPN2 expression by regulating MROH8, which in turn affects the progression and metastasis of pancreatic cancer." (PMID 39434688, 2024).
retinal degeneration (5 papers, 2020 to 2025). Degeneration of the retina. "Most of this calpain activity appears to come from calpain-2, a calpain isoform activated by millimolar Ca2+, that has been implicated repeatedly in retinal degeneration." (PMID 40738887, 2025). "The correlation between retinal degeneration and elevated calpain-2 activation in RhoI255d/+ led us to examine the effect of cGMP analogues on calpain-2." (PMID 40738887, 2025). "High Ca2+-levels likely suppress protective activity of calpain-1 and promote retinal degeneration via activation of calpain-2." (PMID 38303059, 2024). "Alternatively, calpain-2 activation could be a transient event evident only in the early phases of RhoI255d/+ retinal degeneration." (PMID 40738887, 2025). "Previous studies had connected the activity of Ca2+-dependent calpain-type proteases to rd1 retinal degeneration and we hypothesized that the neurodegenerative calpain-2 isoform might be responsible for retinal cell death." (PMID 38303059, 2024). "Thus, we assumed that calpain-2, as part of the proteolytic processes induced by Ca2+, led to retinal degeneration." (PMID 38303059, 2024). "A recent study reported that TUDCA preserved cone photoreceptors and visual function in n-methyl-n-nitrosourea-induced mouse retinal degeneration by suppressing the expression of apoptotic factors (caspase 3, calpain-2, and Bax), increasing SOD protein level, and reducing MDA formation." (PMID 32967221, 2020). "To link calpain-2 with RhoI255d/+ retinal degeneration, we performed TUNEL assays to label dying cells and immunostaining for activated calpain-2 on retinal sections derived from RhoI255d/+ and WT at P20." (PMID 40738887, 2025). "In our study, treatment could not block rd1 retinal degeneration completely, suggesting that beneficial effects resulting from calpain-2 inhibition might have been offset by simultaneous calpain-1 inhibition." (PMID 37189329, 2023).
triple-negative breast carcinoma (5 papers, 2018 to 2025). An invasive breast carcinoma which is negative for expression of estrogen receptor (ER), progesterone receptor (PR), and human epidermal growth factor receptor 2 (HER2). "The high expression of CAPN2 has previously been reported as associated with adverse prognosis in triple-negative breast cancer." (PMID 35625741, 2022). "Therefore, we have generated a panel of CRISPR-Cas9 KO MDA-MB-231 triple-negative breast cancer cell lines for CAPN1, CAPN2, or CAPNS1 genes, which provide models for complete pharmacological inhibition of calpain-1, calpain-2, or both, respectively." (PMID 40940726, 2025).
hepatocellular carcinoma (4 papers, 2017 to 2024). A malignant tumor that arises from hepatocytes. "Downregulation of CAPN2 significantly suppressed migration and invasion ability of hepatocellular carcinoma, and attenuated MMP-2 and MMP-9 secretion." (PMID 29228653, 2017). "Moreover, silencing CAPN2 inhibited the migrative and invasive potentials of hepatocellular carcinoma cells by attenuating the MMPs secretion." (PMID 28280729, 2017). "Accumulating experimental and clinical studies have shown that activation of CAPN2 plays a critical role in tumorigenesis and progression in various tumors, including ovarian cancer, colorectal cancer, gastric cancer, hepatocellular carcinoma, non-small cell lung cancer, and prostate cancer." (PMID 35707527, 2022).
melanoma (4 papers, 2018 to 2023). A malignant, usually aggressive tumor composed of atypical, neoplastic melanocytes. "Thus, the suppressive action of miR-147a on melanoma progression could be negatively altered through the stimulation of LINC00263 expression, which would lead to the upregulation of CAPN2-promoting melanoma proliferation." (PMID 36982460, 2023).
Obesity (4 papers, 2016 to 2025). Accumulation of substantial excess body fat. "Here, we evaluated the contribution of adipocyte-specific calpain-2 on obesity-accelerated AAA in mice." (PMID 41112958, 2025). "In conclusion, obesity impairs autophagy activity, which is mediated by HO-1 inhibition and consequent calpain 2 activation." (PMID 27852058, 2016). "Obesity markedly increased calpain 2 protein expression levels and increased calpain activity in liver compared with those in the lean control, demonstrating that calpain 2 was activated in steatotic livers." (PMID 27852058, 2016). "However, how does obesity enhance the activity of calpain 2 remains unclear." (PMID 27852058, 2016).
colitis (3 papers, 2020 to 2026). Inflammation of the colon. "A previous study has demonstrated the therapeutic potential of CAPN2 inhibitors in murine colitis and colitis-associated cancer, utilizing the azoxymethane/dextran sulfate sodium model to suppress macrophage activation and restrict tumor progression." (PMID 40520022, 2025). "Inhibition of Angiotensin-converting enzyme during colitis (Perindopril: 3 mg/kg/day) prevented the increase in CAPN2, ROS production, autophagy, and t-tubular remodeling." (PMID 42072624, 2026). "Targeting the ITLN1/CAPN2 axis reduced inflammation and PANoptosis significantly and restored mucosal barrier integrity in colitis models, thereby establishing a basis for subsequent clinical application." (PMID 40520022, 2025).
colon cancer (3 papers, 2019 to 2020). "HCT116 have increased levels of CAPN2 in comparison with other colon cancer cell lines, and we also confirmed that protein levels of CAPN1 and CAPN2 are significantly higher than those in HeLa or HEK293 cells while the amount of CAST is moderate." (PMID 33078830, 2020). "For this purpose, we compared the expression levels of CAPN1, CAPN2, CAPNS1 and CAST in different cell lines and chose human HCT116 colon cancer cells." (PMID 33078830, 2020).
colorectal adenocarcinoma (3 papers, 2016 to 2020). The most common type of colorectal carcinoma. "A recent study with a reduced number of patients revealed that the activity and protein levels of calpain-2 were higher in colorectal adenocarcinoma than in normal colonic mucosa from the same patients." (PMID 29507677, 2018). "have reported that CAPN2 protein was overexpressed in human colorectal adenocarcinomas." (PMID 32382656, 2020).
concussion (3 papers, 2017 to 2023). A concussion, also known as a mild traumatic brain injury (mTBI), is a head injury that temporarily affects brain functioning. "Results with calpain-2 knock-out mice or with mice treated with a selective calpain-2 inhibitor indicate that calpain-2 is a potential therapeutic target in various forms of neurodegeneration, including traumatic brain injury and repeated concussions." (PMID 33339205, 2020). "We postulate that calpain-2 activation following TBI (and possibly concussion) could lead to PTPN13 truncation, resulting in increased phosphorylation of c-Abl and its activation." (PMID 28924170, 2017).
head and neck cancer (3 papers, 2021 to 2025). A primary or metastatic malignant neoplasm affecting the head and neck. "Furthermore, hypoxia‐induced HIF1α activation promotes calpain 2, leading to the enzymatic cleavage of talin‐1 and β1 integrin, which facilitates amoeboid migration of breast and head and neck cancer cells." (PMID 40151834, 2025). "Indeed, under hypoxic conditions, induction of calpain-2 switched the collective mode of migration of breast and head and neck cancer cells to an amoeboid metastatic behavior." (PMID 36052226, 2022).